MTOR (mechanistic target of rapamycin kinase)
Diseases named in the same sentence as MTOR in open-access papers (continued):
Sharing a sentence is not in itself a finding about the gene and the disease.
atherosclerosis (continued). "According to the pathway enrichment analysis, we showed that the altered miRNAs in the sperm of BPA‐exposed mice were mainly predicted to target key nodes in the signaling pathways, including PI3K‐Akt, MAPK, mTOR, cAMP, calcium signaling or lipid, and atherosclerosis." (PMID 39792613, 2025). "Finally, treatment of macrophages with mesenchymal stem cell-derived extracellular vesicles (EVs) decreased mTOR phosphorylation, which promoted autophagy-related amelioration of atherosclerosis in diabetic mice." (PMID 40806725, 2025). "Experimental studies suggest that mTOR inhibitors may slow the progression of atherosclerosis, although they frequently induce dyslipidemia." (PMID 40218153, 2025). "Despite these concerns, the clinical significance of mTOR inhibitor-induced dyslipidemia remains unclear, as mTOR inhibition may also suppress pathways that contribute to atherosclerosis progression." (PMID 40003654, 2025). "Notably, PDH activation enhances the assembly of the autophagy initiator ULK1-FIP200-Atg13 complex through the modulation of the AMPK/mTOR signaling pathway, suggesting a potential therapeutic target for Hcy-induced atherosclerosis." (PMID 39980347, 2025). "This study suggests that dysregulated autophagy and high levels of oxidative stress are associated with the development of atherosclerosis, and that lactoferrin therapy might ameliorate atherosclerosis by accelerating the AMPK/mTOR signaling pathway." (PMID 41300435, 2025). "The main pathways involved include the focal adhesion‐PI3K‐Akt‐mTOR‐signaling pathway; AhR; fluid shear stress and atherosclerosis; protein processing in endoplasmic reticulum; thermogenesis; adipogenesis; and several inflammatory‐related pathways (IL‐5, IL‐2, TGF‐β receptor, and IL‐6 signaling)." (PMID 41169019, 2025). "To futher determine whether the NS improves atherosclerosis by affecting the PI3K/Akt/mTOR signaling pathway and autophagy, we evaluated the effects of rapamycin (Ra) and 3-MA on ox-LDL-stimulated macrophages." (PMID 40577270, 2025). "Moreover, TUG1 knockdown in the EC model of atherosclerosis was reported to promote autophagy via the AMPK/mTOR pathway." (PMID 40823532, 2025). "Correspondingly, several reports have demonstrated that 4-PBA effectively attenuates monocyte recruitment byreducing ICAM-1 expression through the mechanistic target of rapamycin (mTOR) signaling pathway, ultimately contributing to a reduction in the pathogenesis of atherosclerosis." (PMID 40661788, 2025). "mTOR plays a significant role in the pathogenesis of atherosclerosis." (PMID 38817407, 2024). "Supplementation of Arg to autophagy-impaired cells with lysosomal insufficiency partially restored mTOR activity and ameliorated cytopathological abnormalities, suggesting that autophagy impairment in atherosclerosis may be ameliorated by Arg supplementation." (PMID 39766264, 2024). "In this context, rapamycin‐mediated inhibition of mTOR pathway could restore neurovascular functions and cardiovascular health in mice model of atherosclerosis." (PMID 37721413, 2024). "Quercetin’s mTOR inhibitory activity may partly contribute to its anti-atherosclerotic effect, which has been observed in animal models and cultured cells of atherosclerosis." (PMID 37108307, 2023). "Targeting the mTOR signaling pathway might exert a protective role against atherosclerosis, however, it is less known whether resveratrol can activate autophagy in vivo." (PMID 38138958, 2023). "Akt/mTOR as part of the PI3K signalling pathway have been known to be linked to different cardiovascular pathology, including cardiac inflammation, fibrosis, hypertrophy, and atherosclerosis." (PMID 37444528, 2023). "Therefore, it can be postulated that Raplink-1, by inhibiting the activation of NF-κB, MAPKs, and mTOR pathways, can be a potential drug candidate against atherosclerosis and IAs." (PMID 37998344, 2023).
atherosclerosis (continued). "Information about development of B cell subpopulations under mTOR modulation could open a whole new field of interactions that need to be further investigated regarding their relevance in myocardial infarction and atherosclerosis." (PMID 35845058, 2022). "Recent studies have shown that Polydatin could enhance autophagy to alleviate atherosclerosis by inhibiting phosphoinositide 3-kinase (PI3K)/protein kinase B(Akt)/mammalian target of rapamycin (mTOR)." (PMID 35845572, 2022). "The present study has revealed that miR-99a-5p might inhibit NLRP3 inflammasome activation and promote macrophage autophagy by targeting mTOR, therefore, alleviating atherosclerosis." (PMID 35968506, 2022). "The mTOR signaling pathway plays an important role in the development of atherosclerosis." (PMID 35163076, 2022). "Little is known about mTOR modulation in neutrophils in atherosclerosis." (PMID 35845058, 2022). "Therapeutic strategies associated with rapamycin have worked well in a number of different diseases, and there is every reason to believe that targeting components of the mTOR pathway may pay off in atherosclerosis as well." (PMID 35163076, 2022). "Inhibition of mTOR or disruption of either complex in EC may further promote the development of atherosclerosis, which is the subject of our ongoing study." (PMID 35869262, 2022). "We suspected that miR-99a-5p might inhibit NLRP3 inflammasome activation and promote macrophage autophagy via constraining mTOR, therefore, alleviating atherosclerosis." (PMID 35968506, 2022). "Therefore, 24 h was selected as a suitable time point to investigate the role of Pim-2 and mTOR signaling pathways in atherosclerosis in subsequent experiments." (PMID 34547720, 2021). "Further studies showed that the expression of proteins related to PI3K/ AKT /mTOR signaling pathway in SIRT1 knockout macrophages was significantly increased, thereby inhibiting macrophage autophagy and eventually causing the formation of atherosclerosis." (PMID 34928817, 2021). "Inhibition of mTOR can defend against the development of atherosclerosis." (PMID 34547720, 2021). "Moreover, a growing body of evidence demonstrates that mTOR inhibitors, such as rapamycin, possess obvious anti-atherosclerotic effects and should be considered supplementary therapy for atherosclerosis." (PMID 34867337, 2021). "In atherosclerosis, lncRNA-FA2H-2 transcriptionally inhibited MLKL expression and loss of lncRNA-FA2H-2 led to the activation of inflammation and inhibition of autophagic flux which is dependent on mTOR pathway." (PMID 34759263, 2021). "mTOR plays an important role in the initiation and progression of atherosclerosis by controlling autophagy and lipid metabolism, representing a promising target site for atherosclerosis treatment." (PMID 34575528, 2021). "Notably the in vivo intervention of VAMP3/SNAP23 by systemic delivery of rapamycin ameliorates thrombi formation, echoing the value of mTOR inhibition in preventing the development of atherosclerosis." (PMID 33224946, 2020). "Rapamycin has the ability to restore impaired autophagy by inhibiting the mammalian target of rapamycin (mTOR), leading to selective clearing of macrophages, increased cholesterol efflux, reduction of apoptotic cells in the plaques, and stabilization of atherosclerosis in ApoE-/- mice." (PMID 31080547, 2019). "Thus, the mTOR depletion of macrophage cells stimulated M1 macrophages and suppresses early atherosclerosis." (PMID 30627532, 2018). "There were different reports on the roles of mTOR on atherosclerosis." (PMID 29724195, 2018). "mTOR inhibitors normally exhibit proautophagic activity thereby suppressing atherosclerosis." (PMID 29270409, 2017). "Treatment with rTM could protect ECs by modulating mTOR-dependent autophagy and restrict atherosclerosis development." (PMID 28607460, 2017). "One possible candidate for atherosclerosis intervention is mTOR, a robust autophagic suppressor." (PMID 29270409, 2017).
atherosclerosis (continued). "In the present study, we investigated whether selective inhibition of PI3K/Akt/mTOR signaling pathway can inhibit the atherosclerosis progression and enhance the stability of atherosclerotic plaques by activation of macrophage autophagy." (PMID 24599185, 2014). "Several clinical studies have demonstrated that mTOR inhibitors, including temsirolimus, sirolimus, and rapamycin, can be employed either as standalone treatments or in conjunction with other therapeutic approaches to address atherosclerosis, autoimmune disorders, and various malignancies." (PMID 40354374, 2025). "It has been demonstrated that mTOR signaling is essential for heart physiological processes regulation such as growth, aging, and lifespan, as well as for playing a pivotal role in pathological conditions such as atherosclerosis and ischemia–reperfusion injury." (PMID 41378307, 2025). "In addition, leucine and isoleucine transported by SLC7A8 are important for maintaining normal metabolic functions of immune cells and regulating cellular activation through pathways, such as mTOR, thereby influencing the progression of cardiovascular diseases, including atherosclerosis." (PMID 40727388, 2025). "Moreover,granuloma-targeted esculetin used alongside metformin improves age-relatedatherosclerosis by modulating AMPK activation and reduces both atherogenesisand the progression of atherosclerosis in obese diabetic rats through modulationof the Sestrin2-mammalian target of rapamycin (mTOR) pathway." (PMID 40351677, 2025). "A potential explanation might be that exosomal miR-186-5p might modulate the LOX-1 and SHIP2-mediated PI3K/AKT/mTOR pathways to facilitate lipid accumulation and promote viability and invasion in VSMCs, thereby contributing to atherosclerosis, which led to the occurrence of AMI." (PMID 38694565, 2024). "Studies in mice also found that FSH could promote lipid synthesis and lipid drome formation in visceral fat through the Gαi/Ca2+/CREB pathway, and activate endothelial VACM‐1through the FSHR/Gas/cAMP/PKA and PI3K/Akt/mTOR/NF‐kB signaling pathways to promote atherosclerosis." (PMID 37221966, 2023). "However, the clinical significance of mTOR inhibitor induced dyslipidemia remains unclear given that mTOR inhibition may actually inhibit pathways involved in the formation of atherosclerosis." (PMID 36017084, 2022). "Taken all together, our findings imply that downregulation of both MOK1 and mTOR genes, together with proatherogenic lipid profile and increased SBP, could contribute to increased risk of atherosclerosis development and cardiovascular complications seen in these patients." (PMID 36042901, 2022). "In summary, during acute inflammation B cell-inhibition attenuates the pro-inflammatory effect of B cells whereas in case of chronic inflammation in atherosclerosis restraining of B cells via mTOR inhibition could hamper protective antibody expression against oxLDL." (PMID 35845058, 2022). "Overexpression of T-cadherin in endothelial cells attenuated insulin-induced PI3K/Akt/mTOR pathway activation and simultaneously reduced insulin-stimulated eNOS activation, migration, and angiogenesis, suggesting the role of endothelial dysfunction induced by T-cadherin in atherosclerosis." (PMID 33767629, 2021). "AMPK may be involved in the metformin-induced modulation of lncRNA because metformin has been shown to inhibit endothelial cell proliferation and atherosclerosis by attenuating the lncRNA TUG1 by activating the AMPK/mammalian target of rapamycin (mTOR) pathway." (PMID 32545901, 2020). "Thus, mTOR depletion stimulates M1 macrophages and suppresses early atherosclerosis." (PMID 30627532, 2018). "Thus mTOR inhibitors are currently being used to treat atherosclerosis in clinical trials." (PMID 29724195, 2018).
atherosclerosis (continued). "Over the last decade, numerous studies have revealed an interplay between miRNAs and the mTOR signaling circuit in the different cardiovascular pathophysiology, like myocardial infarction, hypertrophy, fibrosis, heart failure, arrhythmia, inflammation, and atherosclerosis." (PMID 30305865, 2018). "Furthermore, mTOR mediates cross talk of macrophage polarization and autophagy in atherosclerosis." (PMID 30627532, 2018). "Furthermore, mTOR is able to clean up misfolded proteins (such as Aβ and cerebral amyloid angiopathy) via regulation of autophagy, therefore, it can further reduce athero-sclerosis and preserve neurovascular integrity, e.g., vascular density." (PMID 27829242, 2016). "GSEA revealed upregulation of pathways including platelet activation, fluid shear stress and atherosclerosis, and Rap1 signaling, alongside downregulation of PI3K-Akt and mTOR signaling in patients with PAS." (PMID 41827036, 2026). "The cross-regulation between SUMOylation and phosphorylation in mTOR-mediated cell death could determine whether cells enter apoptotic, necrotic, or autophagic death, especially in the context of cardiovascular diseases like myocardial ischemia or atherosclerosis." (PMID 40734978, 2025). "In addition, hyperinsulinemia can activate the INSR/IRS/PI3K/Akt/mTOR signaling pathway, promoting inhibition of lipolysis and enhancement of lipogenesis in adipocytes, while lipid metabolism disorders remain the core driving factor for lipid accumulation in atherosclerosis." (PMID 41377946, 2025). "Firstly, we employed network pharmacology analysis to identify 113 common targets, including mTOR and CASP3, for NGR1, SSB2, and atherosclerosis from databases such as TCMSP." (PMID 40577270, 2025). "Indeed, numerous clinical trials have investigated the application of mTOR inhibitors, including temsirolimus, sirolimus, and rapamycin, either as standalone treatments or in conjunction with other therapies, for conditions such as atherosclerosis, autoimmune disorders, and malignant tumors." (PMID 40354374, 2025). "In apolipoprotein E‐deficient (APOE−/−) AS mice, Arg2 impairs endothelial autophagy by regulating mTOR and protein kinase AMP‐activated protein kinase (AMPK) and AMPK signalling pathways in advanced atherosclerosis." (PMID 40497340, 2025). "Within this pathway, AGE activation triggers the expression of proteins in the ILK/mTOR/p70S6K signalling pathway, leading to VSMC-to-osteoblast trans-differentiation and cell proliferation, which in turn fosters the progression of atherosclerosis." (PMID 40959494, 2025). "The metabolic processes in cells involve various signaling pathways, with mTOR and AMPK being critical molecules in regulating the role of T-cell metabolic reprogramming in the progression of atherosclerosis (AS)." (PMID 39200308, 2024). "This critical review discusses the role of mTOR, p27kip, and OSM in VSMC proliferation and differentiation followed by the therapeutic potential of targeting these mediators in atherosclerosis to attenuate plaque vulnerability." (PMID 38737892, 2024). "The expression level of Vimentin, N-cadherin, Snail1, ZEB1, PI3K, p-AKT, p-mTOR and BAX in atherosclerosis and chronic stress were higher than that in control group." (PMID 37642954, 2023). "Although the relationship between mTOR activity and endothelial senescence has not been specifically examined in these mouse atherosclerotic lesions, this study provides important evidence of mTOR modulation of endothelial function as a pathogenic determinant of atherosclerosis." (PMID 37894840, 2023). "In atherosclerosis, inhibition of the PI3K/Akt/mTOR pathway by microRNA-126 attenuates endothelial cell injury." (PMID 37085930, 2023).
atherosclerosis (continued). "In atherosclerosis, berberine treatment inhibits inflammation in mouse macrophages (J774A.1) by inducing autophagy through AMPK/mTOR pathway and uncoupling protein 2 in mice." (PMID 34745081, 2021). "Inflammation and apoptosis of vascular endothelial cells play a key role in the occurrence and development of atherosclerosis (AS), and the AMPK/mTOR/Nrf2 signaling pathway plays an important role in alleviating the symptoms of AS." (PMID 34305600, 2021). "Activation of the inflammatory response in atherosclerosis is mainly involved in the Toll-like receptor (TLR), NF-κB, and mTOR-dependent signaling pathways." (PMID 34547720, 2021). "Kaempferol provides benefits in the treatment of atherosclerosis through its antioxidant and anti-inflammatory properties, and it alleviates ox-LDL-induced apoptosis by inhibiting the PI3K/Akt/mTOR pathway and increasing autophagy in human endothelial cells." (PMID 33321972, 2020). "We found that Mapk3 is involved in many important signaling transduction pathways in atherosclerosis progression such as the Toll-like receptor, TGF-β, PI3K-Akt, MAPK, and mTOR signaling pathways." (PMID 31446617, 2019). "Aberrant mTOR activation plays critical roles in the pathogenesis of proinflammatory diseases including lipopolysaccharide induced-ALI, sepsis, atherosclerosis and neurodegenerative diseases, which make mTOR an important therapeutic target for these diseases." (PMID 30422993, 2018). "Previous studies reported that oxLDL actives mammalian target of rapamycin (mTOR) in THP-1cell, and an activator of mTOR inhibits oxLDL-induced autophagy and restricts atherosclerosis in ApoE-knockout mice." (PMID 28777810, 2017). "The KEGG enrichment analysis showed that DEGs were significantly associated with pathways such as longevity regulation, lipid metabolism and atherosclerosis, pluripotency of stem cells, apoptosis, VEGF, HIF-1, TNF, MAPK, Wnt, mTOR, and Hippo signaling pathways." (PMID 40563849, 2025). "Furthermore, metformin attenuates the high-fat diet-induced atherosclerosis, as it can diminish vascular senescence through its effect on the activation of AMPK and it can inhibit the mTOR signaling pathway." (PMID 38138958, 2023). "Our results suggest that CD4+ and CD8+ T cells from AS+ PLWH play a role in cell adhesion, apoptosis and migration processes involved in atherosclerosis, and these atherogenic processes are mediated by the upregulated PI3K-AKT, mTOR, and cytoskeletal signaling pathways." (PMID 36131068, 2022). "However, Hyp-mediated SDT has only been studied in the induction of THP-1 macrophage apoptosis for atherosclerosis treatment, leading to autophagy through the AMPK/mTOR pathway." (PMID 35631688, 2022). "Furthermore, mTOR inhibitor downregulated 14 canonical SGs and 8 exosomes SGs in atherosclerosis, but in MERS infection, mTOR downregulated one canonical SG, two exosomes SGs, and one autophagy SG." (PMID 35320939, 2022). "DLTs may promote autophagy by inhibiting the PI3K/Akt/mTOR signaling pathway, thereby reducing the uptake of ox-LDL by macrophages, which in turn results in the formation of foam cells and the inhibition of atherosclerosis." (PMID 34566648, 2021). "Moreover, mTOR enhances foam cell formation and, inhibiting mTOR, enhances ox-LDL-induced autophagy in vitro and restricts atherosclerosis in ApoE−/− mice." (PMID 31214032, 2019).